BBOF1 (basal body orientation factor 1)
Description:
Plays an essential role in sperm motility and male fertility by stabilizing the sperm flagellar axonemal structure. May be required for the stability of ODF2 and MANS1 proteins. Dispensable for the assembly and function of motile cilia.
Synonyms: C14orf45; CCDC176; FBB10
Tractability: Antibody: the Human Protein Atlas places it where antibodies can reach.
Gene: Protein-coding gene on chromosome 14 (74,019,347 to 74,082,863, forward strand). Ensembl gene ENSG00000119636.
Subcellular location: Cytoplasm, cytoskeleton, cilium basal body; Cytoplasm, cytoskeleton, flagellum axoneme
Subcellular location (Human Protein Atlas): Nucleoplasm; Centriolar satellite; Cytosol; Plasma membrane
Gene Ontology:
Biological process: flagellated sperm motility; motile cilium assembly; sperm axoneme assembly
Cellular component: axoneme; ciliary basal body; sperm flagellum
Genetic constraint (gnomAD): Loss-of-function variants: 29 observed, 38.33 expected, observed/expected ratio (o/e) 0.76, 90% interval 0.56 to 1.03. The upper end of that interval is the gene's LOEUF score, 1.03, which puts it in group 4 of 6, group 1 being the genes least tolerant of losing a copy. Missense variants: 385 observed, 448.69 expected, observed/expected ratio (o/e) 0.86, 90% interval 0.79 to 0.93. Synonymous variants: 156 observed, 150.88 expected, observed/expected ratio (o/e) 1.03, 90% interval 0.91 to 1.18.
Homologues: Orthologues: chimpanzee BBOF1 (99% identical), macaque BBOF1 (96% identical), pig BBOF1 (85% identical), dog BBOF1 (84% identical), rabbit BBOF1 (81% identical), mouse Bbof1 (79% identical), rat Bbof1 (75% identical), tropical clawed frog bbof1 (52% identical), zebrafish bbof1b (38% identical). Paralogues in human: CCDC166 (12% identical).
Diseases named in the same sentence as BBOF1 in open-access papers:
BBOF1 is named in the same sentence as 6 diseases in open-access papers, as found by Europe PMC text mining. Sharing a sentence is not in itself a finding about the gene and the disease. The quoted sentences say what the papers report.
lung carcinoma (1 paper, 2020). "In contrast, blood cell traits and hematological diseases were implicated with a wider range of loci, including TERC, TERT, SENP7, ATM, BBOF1, and MROH8; this result is similar to those for the respiratory function and lung cancers that also involved multiple TL loci." (PMID 32109421, 2020).
BBOF1 also shares sentences with these, for which no sentence is quoted: asthenozoospermia (1 paper); asthma (1); hematological diseases (1); male infertility (1); thymoma (1).